APOE (apolipoprotein E)
Diseases named in the same sentence as APOE in open-access papers (continued):
Sharing a sentence is not in itself a finding about the gene and the disease.
amyloid (continued). "In this study, firstly, we have found an increase in CSF apoE in the TgF344-AD rats, with the documented occurrence of amyloid pathology around 10 months of age." (PMID 36324176, 2022). "In the present work, we can only provide evidence on the predominance of brain amyloidosis over APOE on the sources of brain rhythms and suggest further ad-hoc investigation to carefully disentangle the amyloid-APOE interaction." (PMID 36057818, 2022). "Overall, their experiments suggest that cerebral amyloid load is affected by peripheral ApoE in an isoform-dependent manner (with E3 improving and E4 exacerbating pathology)." (PMID 36195891, 2022). "Second, we did not measure biomarkers related to the prognosis of Alzheimer's pathology, such as apolipoprotein E genotype or amyloid status; therefore, we cannot confirm the pathological mechanisms between physical activity and brain health." (PMID 35911542, 2022). "Apolipoprotein E ε4 (APOE4) is the largest genetic risk factor for development of sporadic AD and has been shown to increase amyloid deposition in a dose-dependent manner, in the asymptomatic, the mild cognitive impairment and the dementia stages of AD." (PMID 36151568, 2022). "As the BACE-1 positive dystrophic neurites are only present around amyloid plaques, this is consistent with overall reductions in amyloid plaque following removal of astrocyte apoE." (PMID 35109920, 2022). "The group validated their findings using an additional model of amyloidosis, namely 5xFAD mice transduced with AAV-albumin-ApoE3 or AAV-albumin-ApoE4, to determine how peripheral ApoE isoforms affect amyloid pathology in the presence of brain ApoE." (PMID 36195891, 2022). "ApoE has been found present in amyloid deposits in AD and other cerebral and systemic amyloidoses, suggesting a general role for ApoE in amyloid diseases as a pathological chaperone." (PMID 36436561, 2022). "Apolipoprotein E and glial fibrillary acidic protein are known biomarkers of AD; the first plays a role in early amyloidosis, cholesterol metabolism, and inflammatory response, and the latter is an established marker of glial-specific neuroinflammation." (PMID 35944844, 2022). "Sample sizes in AD secondary prevention trials can be reduced by the acquisition of dynamic PET scans and/or by restricting inclusion to subjects with intermediate amyloid burden or to APOE-ε4 carriers only." (PMID 33875021, 2021). "Consistent with previous results, ApoE, which is the most abundant co-deposited protein in AApoAII amyloidosis, was significantly increased in the amyloid-induced groups, but was not significantly affected by curcumin." (PMID 33496266, 2021). "Recent studies have highlighted the therapeutic potential of targeting ApoE4, with one such study finding that ApoE immunotherapy was able to ameliorate amyloid-related pathology and protect cerebrovascular function in a mouse model of AD." (PMID 34071762, 2021). "Within the same genotype, there were significant differences in APOE-ε4 status and cognitive diagnosis between the amyloid groups." (PMID 34593890, 2021). "Some of the earliest clues linking APOE with vascular degeneration in AD involved studies demonstrating a link between APOE-ε4 and increased amyloid deposition around blood vessels." (PMID 34238312, 2021). "ApoE-driven AD pathologies differ from pure amyloid pathologies and our prior work indicates apoE can regulate MMP9 disposition in the brain, and the apoE4 isoform in particular is associated with elevated MMP9 levels and activity." (PMID 34034683, 2021). "APOE ε4, a well-known surrogate marker of the presence of amyloid deposits in the brain, was the most powerful predictor of memory decline in our sample." (PMID 33692711, 2021). "To investigate the associative interaction among zinc, apoE, and amyloid-β (Aβ) and its role in amyloid pathogenesis, we performed various biochemical and immunoreactive analyses using brain tissues of Tg2576 mice and synthetic Aβ and apoE peptides." (PMID 31991844, 2020).
amyloid (continued). "Of note, APOE-ε4 showed its strongest effect on amyloid pathology and only a smaller but independent effect on tau pathology, suggesting that APOE-ε4 influences AD pathogenesis more upstream in the amyloid cascade than p.P522R." (PMID 32166339, 2020). "In vivo administration of Ac-hE18A-NH2 to APP/PS1ΔE9 mice for six weeks improved cognition, decreased amyloid plaque deposition, reduced activated microglia and astrocytes, and increased CNS apoE levels." (PMID 32882843, 2020). "Studies in human and transgenic mice have shown that the Aβ levels in the brain and the amyloid plaque load are ApoE isoform-dependent (ε4>ε3>ε2), suggesting that ApoE plays an important role in the regulation of Aβ metabolism, aggregation, and deposition." (PMID 33536896, 2020). "Nuclear receptor agonists upregulate ABCA1, ABCG1, and APOE gene expression, which increases apoE lipidation, facilitates Aβ clearance, reduces amyloid pathology, and reverses memory deficits in an amyloid mouse model." (PMID 32882843, 2020). "This implicates TREM2 in the maintenance of the microglial response to amyloid pathology, further connecting APOE, TREM2, microglia function, and amyloid pathology." (PMID 32703241, 2020). "In amyloid mouse models, APOE upregulation is a major molecular signature of the subtype of microglia known as disease-associated microglia (DAM)." (PMID 33148290, 2020). "There are further indications that APOE ε4 modifies the relationship between amyloid load and cognitive function." (PMID 32591008, 2020). "In AD, apoE serves as a pathological chaperone to stimulate Aβ aggregation and fibrillation in amyloid pathogenesis." (PMID 31991844, 2020). "A panel of proteins (n = 44), along with age and apolipoprotein E (APOE) ε4, predicted brain amyloid deposition with good performance in both the discovery group (area under the curve = 0.78) and the replication group (area under the curve = 0.68)." (PMID 31495601, 2019). "This study investigates how APOE modulates neuronal function integrity during normal aging and in the context of amyloidosis." (PMID 30760557, 2019). "Insoluble extracellular Aβ deposits forming amyloid plaques and accumulation of ApoE and GFAP in the brain are all key histopathological hallmarks of AD." (PMID 32082134, 2019). "We partially recapitulated the isoform-dependent effect of APOE on Aβ accumulation in a model of amyloidosis." (PMID 31623648, 2019). "Intriguingly, the effects of APOE on amyloidosis appear to be both isoform- and quantity-dependent, as reduction of apoE3 and apoE4 levels through genetic or pharmacologic manipulations results in reduction of cerebral amyloid plaque load." (PMID 31623648, 2019). "An antagonistic pleiotropy model for the role of apoE in AD amyloidosis is consistent with etiology data and evolutionary explanations for the protein’s involvement across multiple age-dependent inflammation diseases." (PMID 30983989, 2019). "An example is the relationship between APOE ɛ4 and amyloid: while APOE ɛ4 is a key driver of amyloidosis, the measured effect of amyloid load on cognition is significantly stronger than the impact of APOE ɛ4 on cognition." (PMID 30783207, 2019). "The results showed different pattern of APOE contribution in PRS risk predictions of AD/MCI and amyloid deposition." (PMID 31199530, 2019). "The PCC/PrC node of DMN received great attention showing significant modification in normal aging and moreover in AD, indicating amyloid deposition and reduction of metabolism, especially in APOE E4 patients." (PMID 29568755, 2018). "On the other hand, effects of viral delivery of human ApoE assessed in APP transgenic mice showed reduced amyloid plaque load by ApoE2 and increased plaque load by ApoE4." (PMID 30541602, 2018). "When given at pre-plaque stage or after plaque deposition, an anti-mouse ApoE antibody decreased amyloid plaque load and improved brain functional connectivity and cognition in an APP transgenic mouse model." (PMID 30541602, 2018).
amyloid (continued). "Diverse molecular mechanisms have been postulated for ApoE’s effects, ranging from direct transcriptional repression to facilitating amyloid plaque development in damaged neurons." (PMID 28321820, 2017). "The present study aims to examine the link between amyloid deposition and ApoE and EEG measures such as power but also functional coherence and effective connectivity." (PMID 29081745, 2017). "The fact that apoE and apoJ interfere with Aβ fibril formation explains why they are co-localized with Aβ amyloid plaques in AD brain." (PMID 29155887, 2017). "In people who are APOE ε4 positive, more amyloidosis is found, meaning there is an additive effect of age and APOE ε4." (PMID 28893185, 2017). "In mouse models of AD-relevant amyloid deposition, direct LXR/RXR agonists increase lipidated apoE, improve memory performance, and can lower amyloid load, suggesting that increasing the levels of functional, lipid-carrying apoE is of therapeutic benefit." (PMID 27598782, 2016). "The prevalence of PET amyloid-positivity is always above 90% from age 50 to age 90 in clinically diagnosed ApoE ɛ 4-positive AD potients." (PMID 27891223, 2016). "Decreased retinal melanopsin expression, together with amyloidosis and tau deposition, was evident in ApoE−/− mice." (PMID 27824104, 2016). "To investigate the co-aggregation of different apoE in plaques and CAA, we assessed co-localization of apoE and amyloid in these two lesions in the same brain." (PMID 26556230, 2015). "Perivascular drainage of Aβ is thought to play a critical role in the clearance of Aβ and APOE has been shown to co-localize to perivascular spaces as well as with astrocytic endfeet in transgenic mouse models of amyloidosis." (PMID 24587158, 2014). "In a postmortem study of patients with AD, Chalmers and colleagues reported that parenchymal amyloid load was more predictive of white matter degeneration in the frontal lobe than degenerative vascular disease, cerebral amyloid angiopathy or APOE ε4 genotype." (PMID 25129614, 2014). "Amyloidosis depots contain not only the major fibrillar component but also minor nonfibrillar components such as glycosaminoglycans (GAGs), apolipoprotein E (apoE), and serum amyloid P (SAP) components." (PMID 23762130, 2013). "The effects of ApoE on Aβ depositions are supported by the observation that intake of sugar-sweetened water induces amyloidosis and memory impairment and increases ApoE levels in the brain of a transgenic mouse model of AD." (PMID 23210692, 2012). "In other words, even when an ε2 homozygote had evidence of amyloidosis, this individual was positioned lower in terms of the degree of pathology being detected than those with other APOE genotypes (though with only one Aβ + ε2/ε2 observation, statistical analysis of these differences was precluded)." (PMID 41522467, 2026). "Our data extend this by showing that APOE ε4 carriers with a heavy amyloid burden exhibit the most pronounced gut dysbiosis, suggesting that APOE ε4 and amyloid pathology may synergistically disrupt the microbiome." (PMID 41037094, 2025). "In essence, APOE ε4 carriers displayed a more pronounced “amyloid-associated dysbiosis” than non-carriers." (PMID 41037094, 2025). "Furthermore, Matrix metalloproteinase-9 and Apolipoprotein E influence curcumin, which has potential therapeutic benefits in reducing oxidative stress and amyloid plaque formation in VaD due to its anti-inflammatory and antioxidant properties." (PMID 41032496, 2025).
amyloid (continued). "For instance, amyloidosis-targeted and anti-APOE therapies could be explored to prevent post-infection neurodevelopmental sequelae observed in some children after CM recovery." (PMID 39023792, 2025). "Alterations in vessel hemodynamics, angiogenesis, vascular cell function, vascular coverage, blood-brain barrier permeability, and immune cell migration may be interconnected with amyloid toxicity, oxidative stress, and the apolipoprotein E (APOE) genotype." (PMID 40832438, 2025). "APOE ε4 impairs Aβ clearance, resulting in earlier and more extensive amyloid deposition, which may in turn trigger stronger tau phosphorylation and the release of tau into circulation." (PMID 41163175, 2025). "In summary, sex differences in AD biomarkers among individuals with SCD remain inconclusive, although some studies suggest that females, especially APOE ε4 carriers, may present with greater tau and amyloid pathology than men." (PMID 41313305, 2025). "Current results suggest that in women carrying at least one APOE ε4 allele, MHT use may be associated with elevated amyloid deposition and AD pathology." (PMID 39783876, 2025). "Indeed, transcriptomic studies in 5XFAD mice have identified TREM2 and APOE as two of the most upregulated genes in microglia actively engaged in amyloid phagocytosis, underscoring their importance in microglial activation and function in AD pathology." (PMID 40149001, 2025). "We investigated whether expressing APOE isotypes in astrocytes alone could restore amyloid plaque formation and assess the involvement of microglia." (PMID 39528861, 2024). "Apolipoprotein E (ApoE) is involved in cholesterol transport among cells and also plays an important role in amyloid formation, co-depositing with amyloid fibrils in various types of amyloidosis." (PMID 38877049, 2024). "Considering that Leu185–Arg230 could be an amyloidogenic area, it is hypothesized that the reduced binding activity of ApoE to lipids on its C-terminal domain results in the development of cholesterol granulomas and amyloidosis." (PMID 38877049, 2024). "The risk of amyloid-related imaging abnormalities (ARIAs) is significantly higher in APOE ε4 homozygotes than in heterozygotes and non-carriers." (PMID 39200803, 2024). "Additionally, the ApoE genotype has been demonstrated to regulate the progression of amyloid pathology in the brain, with different human ApoE subtypes primarily affecting Aβ clearance and aggregation and ultimately influencing AD pathogenesis." (PMID 38360834, 2024). "Interestingly, we observed that APOE secreted from astrocytes colocalized with X-34 positive fibrillar amyloid plaques." (PMID 39528861, 2024). "In addition, plasma‐derived apoE O‐glycosylation levels differ significantly by APOE genotype and CSF amyloid status, with APOE ε4/ε4 carriers showing low apoE O‐glycosylation." (PMID 39031528, 2024). "Thus, APOE not only influences abnormal lipid metabolism but also drives amyloidosis, and future studies should further address the link between the two effects." (PMID 39717390, 2024). "The brain projection was not significantly influenced by the presence of amyloid (p = 0.99) or the presence of APOE ε4 allele (p = 0.53)." (PMID 39516511, 2024). "The cognitive projection was significantly influenced by the presence of amyloid (p = 9.6e–4) but not by the APOE ε4 allele (p = 0.31)." (PMID 39516511, 2024). "Given our findings for both amyloid-mediated and direct effects of APOE on tau, gene therapies that leverage protective e2 mechanisms may have a global protective impact on limiting amyloid and tau across the brain." (PMID 36597122, 2023). "Identification of such a “proteomic amyloid signature” (including serum amyloid P component (SAP), ApoE, and ApoA-IV) may be a more sensitive method for the diagnosis of amyloidosis than CR staining." (PMID 36902083, 2023).
amyloid (continued). "Similarly, a clear co-localization of amyloid plaques, ApoE and Iba1 was also observed in brain of AD patient, whereas in healthy brain, ApoE staining was slight." (PMID 37145189, 2023). "A viral-mediated overexpression of APOE ε2 in amyloid mouse model brains led to a reduction of the Aβ burden, which might be attributed to an increased Aβ clearance in APOE ε2 expressing animals." (PMID 36703235, 2023). "Evidence shows that the strongest genetic risk factor for late-onset AD is the E4 allele of the cholesterol transporter APOE (APOE4), besides, APOE4 could promote amyloid aggregation and impair clearance from the brain directly binding to Aβ." (PMID 36465634, 2022). "In summary, our findings support the hypothesis that ApoE plays a major role in amyloid deposition in various amyloid diseases." (PMID 36436561, 2022). "ApoE depletion in AD mouse models has been accomplished using antisense oligonucleotides, immunotherapies, or tamoxifen-inducible APOE repression, each of which was found to reduce amyloid pathology." (PMID 35768831, 2022). "It is well established that apoE co-deposits with Aβ in amyloid plaques." (PMID 36348357, 2022). "Moreover, only hippocampus and lateral ventricles volumes were significantly associated with amyloid status, CDR and APOE e-4 A similar association is shown for the global GM volume computed with the CAT12 segmentation." (PMID 35839659, 2022). "Additionally, while the immunostaining showed that overall apoE levels were greatly reduced in the Cre + mice, there were still intense foci of apoE staining co-localized with the X-34+ amyloid plaques, similar to what was observed in the Cre- mice." (PMID 35109920, 2022). "The most crucial process of APOE related to amyloid pathology remains unclear, and additional studies are required to increase the knowledge about the effect of APOE and amyloid pathology in AD." (PMID 36153580, 2022). "Three, can amyloidosis and cell proliferation in cancer be reversed targeting ApoE/LRP8?" (PMID 36012187, 2022). "However, because insoluble apoE in the guanidine fraction is likely apoE bound to amyloid plaques, the decrease in insoluble apoE in the guanidine fraction of the Cre + mice is likely due to overall Aβ plaque levels being decreased." (PMID 35109920, 2022). "Genetic deletion of the murine ApoE gene (which is expressed as a single isoform) in mouse models overexpressing mutant forms of the human Aβ precursor protein (AβPP) results in inhibition of Aβ deposition or in a decrease in amyloid plaques." (PMID 36436561, 2022). "With the targeted removal of astrocytic APOE resulting in a significant reduction in overall apoE levels, we investigated what impact this reduction might have on the deposition of Aβ into X34+ fibrillar amyloid plaques." (PMID 35109920, 2022). "Our study suggests that SCFA-regulated pathways might be promising drug targets in the peripheral circulation for early-stage AD to prevent microglial activation, ApoE production, and the development of amyloid pathology." (PMID 33845942, 2021). "Together with our immunoreaction experiments, these studies support the idea that direct interactions between zinc and apoE might participate in amyloid pathogenesis." (PMID 31991844, 2020). "However, the influence of cooperative interaction between zinc and apoE in amyloid pathology remains largely unexplained." (PMID 31991844, 2020). "APOE may have a dual role and control the transcriptional/translational response of microglia to amyloid as well as amyloid plaque compactness that directs microglial recruitment and thus creates a regulatory feedback-loop." (PMID 32510331, 2020). "For all behavioral and histological analysis we tested the mice at an average age of 6.5 months when amyloid pathology is readily detectable in mice expressing either APOE isoform and we previously have shown significant cognitive differences between APP/E3 and APP/E4 mice." (PMID 32703241, 2020).